Y_RNA (Y RNA )
Gene: Miscellaneous RNA gene on chromosome 16 (18,397,937 to 18,398,036, forward strand). Ensembl gene ENSG00000206927.
Homologues: Orthologues: chimpanzee Y_RNA (98% identical), macaque Y_RNA (93% identical), dog Y_RNA (80% identical), pig Y_RNA (80% identical). Paralogues in human: Y_RNA (100% identical), Y_RNA (98% identical), Y_RNA (84% identical), Y_RNA (83% identical), Y_RNA (82% identical), RNY3 (81% identical), Y_RNA (81% identical), RNY3P1 (80% identical), RNY3P4 (80% identical), Y_RNA (80% identical), RNY3P11 (79% identical), Y_RNA (79% identical), and 92 more.